COPA (coat protein complex I subunit alpha)
Description:
The coatomer is a cytosolic protein complex that binds to dilysine motifs and reversibly associates with Golgi non-clathrin-coated vesicles, which further mediate biosynthetic protein transport from the ER, via the Golgi up to the trans Golgi network. Coatomer complex is required for budding from Golgi membranes, and is essential for the retrograde Golgi-to-ER transport of dilysine-tagged proteins. In mammals, the coatomer can only be recruited by membranes associated to ADP-ribosylation factors (ARFs), which are small GTP-binding proteins; the complex also influences the Golgi structural integrity, as well as the processing, activity, and endocytic recycling of LDL receptors (By similarity). Xenin stimulates exocrine pancreatic secretion. It inhibits pentagastrin-stimulated secretion of acid, to induce exocrine pancreatic secretion and to affect small and large intestinal motility. In the gut, xenin interacts with the neurotensin receptor.
Synonyms: Alpha-COP; HEP-COP; AIAISD; AIAISD1; AILJK
Tractability: Small molecule: a structure with a bound ligand is known. Antibody: UniProt places it where antibodies can reach, with medium confidence; its Gene Ontology location is reachable by antibodies, with medium confidence. PROTAC: ubiquitination databases record sites on it; its protein half-life has been measured.
Gene: Protein-coding gene on chromosome 1 (160,288,594 to 160,343,566, reverse strand). Ensembl gene ENSG00000122218.
Subcellular location: Cytoplasm; Golgi apparatus membrane; Cytoplasmic vesicle, COPI-coated vesicle membrane; Secreted (Xenin)
Subcellular location (Human Protein Atlas): Cytosol; Nucleoplasm; Golgi apparatus; Predicted to be secreted
Pathways (Reactome):
Vesicle-mediated transport: COPI-dependent Golgi-to-ER retrograde traffic; COPI-mediated anterograde transport
Gene Ontology:
Molecular function: protein binding; mRNA binding; structural molecule activity
Biological process: pancreatic juice secretion; endoplasmic reticulum to Golgi vesicle-mediated transport; intra-Golgi vesicle-mediated transport; intracellular protein transport; retrograde vesicle-mediated transport, Golgi to endoplasmic reticulum; vesicle-mediated transport
Cellular component: COPI vesicle coat; cytoplasm; extracellular exosome; extracellular region; growth cone; membrane; cytosol; endoplasmic reticulum membrane; Golgi membrane; transport vesicle; COPI-coated vesicle; COPI-coated vesicle membrane; Golgi apparatus; membrane coat
Genetic constraint (gnomAD): Loss-of-function variants: 8 observed, 146.91 expected, observed/expected ratio (o/e) 0.0545, 90% interval 0.031 to 0.098. The synonymous counts are far from expectation, so gnomAD's model fits this gene poorly and the ratio says little. Missense variants: 1,011 observed, 1,524.3 expected, observed/expected ratio (o/e) 0.66, 90% interval 0.63 to 0.7. Synonymous variants: 440 observed, 546.62 expected, observed/expected ratio (o/e) 0.8, 90% interval 0.74 to 0.87.
Homologues: Orthologues: chimpanzee COPA (99% identical), rabbit COPA (99% identical), guinea pig COPA (99% identical), dog COPA (99% identical), macaque COPA (99% identical), mouse Copa (98% identical), pig COPA (98% identical), rat Copa (98% identical), tropical clawed frog copa (89% identical), zebrafish copa (87% identical), Drosophila melanogaster alphaCOP (71% identical), Caenorhabditis elegans copa-1 (59% identical). Paralogues in human: COPB2 (19% identical).
Diseases named in the same sentence as COPA in open-access papers:
COPA is named in the same sentence as 86 diseases in open-access papers, as found by Europe PMC text mining. Sharing a sentence is not in itself a finding about the gene and the disease. The quoted sentences say what the papers report.
COPA syndrome (27 papers, 2017 to 2026). "COPA syndrome is a rare monogenic autoinflammatory disease due to heterozygous mutations in COPA, encoding the coatomer subunit α." (PMID 41805977, 2026). "COPA syndrome is a monogenic autoinflammatory disease originally described in 2015 due to heterozygous mutations in the gene COPA, encoding the coatomer subunit α." (PMID 41395910, 2025). "Recently, mutations in the C-terminal part of COPA have been published as causative of COPA syndrome." (PMID 41395910, 2025). "COPA syndrome is a rare autoinflammatory disorder caused by mutations in the COPA gene, which encodes a protein involved in intracellular protein transport." (PMID 40231289, 2025). "The location of these COPA mutations is directly linked to the pathogenesis of COPA syndrome as they affect the WD40 domain, which plays a key role in the recognition of STING for its retrograde transport." (PMID 41395910, 2025). "COPA syndrome results from mutations in the COPA gene and defective retrograde transport of proteins between the Golgi and the ER, resulting in mislocalization of immune signaling proteins, leading to chronic inflammation." (PMID 40231289, 2025). "The first report of COPA syndrome was made in 2015, following the discovery of mutations in the coatomer subunit alpha (COPA) gene in five families." (PMID 39767180, 2024). "COPA syndrome, an inflammatory Mendelian disease, is caused by missense mutations in the coatomer subunit α (COPA) protein, which is a component of coat protein complex I (COPI) and, as such, participates in the retrograde Golgi-to-ER trafficking." (PMID 39767180, 2024). "According to the latest reports, heterozygous mutations in the COPA gene (chr.1 q23.2) result in COPA syndrome, a rare autoinflammatory disease inherited in an autosomal dominant manner with incomplete penetrance and variable expression." (PMID 39620212, 2024). "Mutations in the COPA gene are associated with COPA syndrome, an autoimmune interstitial lung, joint, and kidney monogenic disease, found mainly in children." (PMID 39620212, 2024). "The COPA variants identified in COPA Syndrome fall in the WD40 domain of the protein, which is responsible for recognizing and binding cargo by their dilysine motifs." (PMID 36748043, 2023). "Researchers have shown that the first four variants identified in COPA Syndrome (K230N, R233H, E241K, and D243G) result in an impaired ability of COPA to recognize and bind its cargo properly (Watkinet al.2015)." (PMID 36748043, 2023). "COPA syndrome is a rare disease with autoimmune and autoinflammatory traits caused by heterozygous loss-of-function mutations in the coatomer subunit alpha (COPA) gene and considered as a monogenic interferonopathy." (PMID 36991303, 2023). "To further study inflammation in the context of COPA syndrome, we generated overexpression plasmids encoding the previously published loss of function COPA mutations E241K and R233H1." (PMID 35484149, 2022). "COPA syndrome is an autoimmune disease caused by COPI coat complex subunit alpha (COPA) mutations with persistent release and accumulation of IFN-1." (PMID 36545321, 2022). "This approach was based on the assumption that the reduced target protein binding efficiency of loss of function mutations identified in COPA syndrome patients can be mimicked by the reduction of wild-type (WT) COPA protein levels." (PMID 35484149, 2022). "Like SAVI, COPA syndrome is a monogenic autoinflammatory disease caused by the mutation of the Coatomer protein complex subunit alpha (COPA) gene, characterized by arthritis and lung disease." (PMID 34956229, 2021). "COPA mutations have recently been revealed to cause autoimmune interstitial lung, joint, and kidney disease (COPA syndrome)." (PMID 32318090, 2020).
COPA syndrome (continued). "We report two COPA syndrome patients from the two generations in the same family (son and father) with a novel gene mutation in the COPA gene and a different clinical presentation, distinct from the clinical phenotypes reported in the literature." (PMID 31455335, 2019). "We here report two patients with COPA syndrome within the same family with a novel COPA gene mutation different than the heterozygous monogenic missense mutations in the WD40 domain and distinct from the clinical phenotypes reported in the literature so far." (PMID 31455335, 2019). "To date, four missense mutations in COPA have been reported in a single publication in individuals within five families with COPA syndrome." (PMID 29137621, 2017). "In fact, MTX therapy has also been used to alleviate symptoms of arthritis in patients who suffer from COPA syndrome, an immune dysregulatory disease caused by defective COPA gene variants." (PMID 28235825, 2017). "It is also termed COPA syndrome since it is caused by heterozygous missense mutations in the COPA gene (specifically in the WD40 domain of the coatomer subunit alpha)." (PMID 29137621, 2017). "Rare missense mutations in the gene encoding coatomer subunit alpha (COPA) have recently been shown to cause autoimmune interstitial lung, joint and kidney disease, also known as COPA syndrome, under a dominant mode of inheritance." (PMID 29137621, 2017). "For example, COPA syndrome, characterized by high levels of type I interferon and interferon-stimulated genes, is caused by the heterozygous mutations in COPA, which encodes a subunit of the COPI trafficking complex that mediates transport from the Golgi to the ER." (PMID 39933900, 2025). "Coatomer protein complex subunit alpha (COPA) syndrome is caused by a heterozygous mutation in the COPA gene, which encodes the α-subunit of coat protein complex I (COPI) and is involved in the trafficking of membranes from the Golgi apparatus to the endoplasmic reticulum." (PMID 38914753, 2024). "In a recent report, a 10-year-old girl who was diagnosed with lupus nephritis and carried a mutation in the COPA gene indicated that COPA syndrome could also be a cause of lupus nephritis." (PMID 38914753, 2024). "In addition, like SAVI, COPA syndrome derives from missense mutations in the COPA gene encoding the COPα protein subunit of the COPI complex, which regulates the transportation of STING in the ER." (PMID 37122745, 2023). "Thus COPA mediates maintenance of immune homeostasis via regulating the STING transport to the Golgi-complex and the dysregulation of COPA overactivates STING causing immune dysregulation in the COPA syndrome." (PMID 33643304, 2020). "COPA syndrome is a recently defined disorder of immune system which has been associated with type 1 interferon activation This disease is an autosomal dominant inherited disease and caused by mutations in COPA gene, which encodes alpha subunit of coatomer protein complex I (COPα)." (PMID 30560109, 2018). "Structural analysis using AF2M highlights the critical role of HAQ-STING in modifying COPA conformation and mitigating COPA syndrome pathology." (PMID 40231289, 2025). "One of these is coatomer subunit alpha (COPA) syndrome, classified by the International Union of Immunologic Societies (IUIS) expert committee on inborn errors of immunity under the “auto-inflammatory, other” category." (PMID 39620212, 2024). "Disease in COPA-deficient mice can be rescued by genetic knockout or pharmacological inhibition of STING signaling, establishing STING as a critical driver of COPA syndrome." (PMID 36705629, 2023). "In particular, inactivating mutations in coatomer subunit α (COPA), which mediates retrograde transport from the Golgi to ER, have been shown to drive STING‐dependent inflammation in COPA syndrome." (PMID 37139896, 2023).
COPA syndrome (continued). "In line with our data, spontaneous Golgi accumulation of STING in cell lines overexpressing COPA mutants and COPA syndrome patient cells has recently been shown in other studies published while our manuscript was under review." (PMID 35484149, 2022). "In COPA syndrome, there is impaired STING recycling amongst other stressors from impaired Golgi-to-ER trafficking due to the effect of a pathogenic COPA variant on the COPI trafficking complex." (PMID 35693769, 2022). "Mutation of the COPA gene, encoding one of the COP-I subunits (α-COP), causes an immune dysregulatory disease known as COPA syndrome." (PMID 33397928, 2021). "In the mouse model of COPA syndrome, mutant COPA impaired the thymic selection of T cells, characterized by an increase of IFN-γ and IL-17A-secreting CD4+ T cells and IFN-γ-secreting CD8+ T cells, and a decrease of regulatory T cells in peripheral tissues." (PMID 34956229, 2021). "In COPA syndrome, ILD gradually develops over time, possibly as a result of ongoing bleeding and inflammation as well as an as-yet-undiscovered direct lung injury caused by COPA mutations." (PMID 39767180, 2024). "Since COPA is involved in Golgi to ER retrograde trafficking and ER stress is heightened in COPA Syndrome patient cells, we hypothesized that ourcopa-1mutants may have a phenotype when ER stress is induced." (PMID 36748043, 2023). "It appears that COPA gene mutations do not show a genotype-phenotype correlation for the typical symptoms of COPA syndrome, although the strength of any conclusive statement is limited due to the recent identification of this disease and a limited number of patients." (PMID 39620212, 2024). "The sisters with a mutation in the COPA gene in this case report did not present with “typical COPA syndrome” but it is well-known that a monogenic disease may have different phenotypes." (PMID 39620212, 2024). "COPA syndrome, also known as an autoimmune interstitial lung, joint, and kidney disease (MIM # 616414), is a rare autosomal dominant disorder caused by heterozygous missense variants located in exons 8 and 9 of the COPA gene and highly conserved WD40 domain of the COPA protein." (PMID 39620212, 2024). "Indeed, STING activation is a key driver of the pathogenesis of COPA syndrome, and a recent report suggested that the presence of the common HAQ STING allele confers complete protection against the development of clinical disease in the context of pathogenic heterozygous mutations in COPA." (PMID 41805977, 2026). "However, with endogenous levels of STING expression, as in HEK293 cells or HEK293T cells stably expressing STING-GFP, overexpressed COPA mutations cannot drive inflammation, likely because an essential player of the COPA syndrome pathology is lacking in these cell lines." (PMID 35484149, 2022).
Arthritis (8 papers, 2017 to 2025). Inflammation of a joint. "COPA variants are associated with interstitial lung disease and haemorrhage, arthritis and nephritis." (PMID 40465409, 2025). "Mutations in the N-terminal WD40 domain of coatomer protein complex subunit α (COPA) cause a type I interferonopathy, typically characterized by alveolar hemorrhage, arthritis, and nephritis." (PMID 38175705, 2024). "Variants in the COPA genes (OMIM 601924) have been associated with impaired intracellular communication, which resulted in impaired inter‐organelle transport, increased ER stress, and cytokine generation, causing hereditary autoimmune lung disease and arthritis." (PMID 32869858, 2020). "Mutant COPA has been previously shown to impair the assembly of proteins targeted for transport and to lead to ER stress and UPR activation in hereditary autoimmune-mediated lung disease and arthritis." (PMID 36869179, 2023).
autoimmune disease (7 papers, 2015 to 2025). A disorder resulting from loss of function or tissue destruction of an organ or multiple organs, arising from humoral or cellular immune responses of the individual to their own tissue constituents. "Research indicates that mutations in COPA are associated with autoimmune diseases and that COPA mutants induce the production and signaling of Type I IFN in a dominant-negative manner through STING, thereby controlling the autoimmune inflammation process." (PMID 41472131, 2025). "Heterozygous missense mutation in WD40 domain of the COPA gene is related to the COPA syndrome, which is a Mendelian syndrome with autoimmune disorder featured with interstitial lung disease, joint inflammation, and elevated type I-IFN signaling." (PMID 35803579, 2022). "A splicing site variant of COPA, a gene-related to autoimmune diseases, was identified as a de novo occurrence in a patient with delayed development and epilepsy without other abnormalities." (PMID 36619507, 2022). "More recently, four deleterious variants within COPA have been linked to an autoimmune disease characterized by high-titer autoantibodies, interstitial lung disease, and inflammatory arthritis." (PMID 26292806, 2015). "Importantly, we made these observations not only in the presence of pathogenic COPA mutations that cause autoimmune disease, but also after administering a systemic STING agonist being trialed for cancer patients." (PMID 40569687, 2025). "Several mutations in the COPA gene (coding for coatomer protein complex subunit alpha) that affect the same COPA functional domain have been identified in patients with autoimmune diseases characterized by high-titer autoantibodies, inflammatory arthritis, and interstitial lung disease." (PMID 31717602, 2019). "Thus, mutant COPA does appear to affect immune pathways which can lead to autoimmune disease and our findings suggest that differential epigenetic regulation of COPA may play a role in hypersensitivity, though further research is necessary to elucidate this role." (PMID 26292806, 2015).
interstitial lung disease (6 papers, 2015 to 2026). A diverse group of lung diseases that affect the lung parenchyma. "The results of a recent randomized controlled phase 2 trial of HCQ in 35 patients with various forms of interstitial lung disease (caused by the pathogenic variants of SFTPC, ABCA3, NKX2.1, TBX4, COPA, etc.)did not identify an overall HCQ treatment effect." (PMID 41181172, 2025).
Autoimmunity (4 papers, 2016 to 2025). The occurrence of an immune reaction against the organism's own cells or tissues. "We described 3 heterozygous mutations in the C-terminal domain (CTD) of COPA (p.C1013S, p.R1058C, and p.R1142X) in 6 children from 3 unrelated families with a similar syndrome of autoinflammation and autoimmunity." (PMID 38175705, 2024). "Here, we report 3 previously undescribed heterozygous mutations, 1 private nonsense and 2 missense, in the CTD of COPA in 6 children affected by a syndrome of autoinflammation and autoimmunity." (PMID 38175705, 2024). "This has already been shown for COPA but is probably also the case in a few other monogenic forms of autoimmunity (e.g., APS1, IPEX, and CTLA4), in which relatively common autoimmunity-associated HLA alleles probably modify the risk of developing autoimmunity to specific autoantigens." (PMID 41608500, 2025).
Immunodeficiency (4 papers, 2022 to 2025). Failure of the immune system to protect the body adequately from infection, due to the absence or insufficiency of some component process or substance. "COPA was reported to be an essential gene in developing of systemic immune disorders such as psoriasis, lung immune disorders, and others, and it can be linked to immune pathology in MS and AD." (PMID 37286172, 2023). "This suggests defective innate immune defence mechanisms upon lost function of COPA and COPG1, which could perhaps contribute to immunodeficiency of COPG1 (K652E) patients." (PMID 35484149, 2022).